CD226 (CD226 molecule)
Description:
Cell surface receptor that plays an important role in the immune system, particularly in intercellular adhesion, lymphocyte signaling, cytotoxicity and lymphokine secretion mediated by cytotoxic T-cells and NK cells. Functions as a costimulatory receptor upon recognition of target cells, such as virus-infected or tumor cells. Upon binding to its ligands PVR/CD155 or NECTIN2/CD112 on target cells, promotes the cytotoxic activity of NK cells and CTLs, enhancing their ability to kill these cells. Mechanistically, phosphorylation by Src kinases such as LYN of FYN, enables binding to adapter GRB2, leading to activation of VAV1, PI3K and PLCG1. Promotes also activation of kinases ERK and AKT, as well as calcium fluxes (By similarity).
Synonyms: DNAM-1; DNAM1; PTA1; TLiSA1
Tractability: Antibody: UniProt places it where antibodies can reach, with high confidence; its Gene Ontology location is reachable by antibodies, with high confidence; UniProt predicts a signal peptide or a membrane-spanning region; the Human Protein Atlas places it where antibodies can reach. PROTAC: ubiquitination databases record sites on it.
Gene: Protein-coding gene on chromosome 18 (69,831,158 to 69,961,803, reverse strand). Ensembl gene ENSG00000150637.
Subcellular location: Cell membrane
Subcellular location (Human Protein Atlas): Plasma membrane; Centriolar satellite; Nucleoplasm
Pathways (Reactome):
Immune System: Immunoregulatory interactions between a Lymphoid and a non-Lymphoid cell
Gene Ontology:
Molecular function: cell adhesion molecule binding; identical protein binding; integrin binding; protein binding; protein kinase binding; signaling receptor activity
Biological process: natural killer cell mediated cytotoxicity; positive regulation of Fc receptor mediated stimulatory signaling pathway; positive regulation of immunoglobulin mediated immune response; positive regulation of mast cell activation; positive regulation of natural killer cell mediated cytotoxicity; positive regulation of natural killer cell mediated cytotoxicity directed against tumor cell target; positive regulation of T cell receptor signaling pathway; cell adhesion; cell recognition; signal transduction; positive regulation of natural killer cell cytokine production
Cellular component: cell surface; plasma membrane; external side of plasma membrane; membrane raft
Genetic constraint (gnomAD): Loss-of-function variants: 19 observed, 27.55 expected, observed/expected ratio (o/e) 0.69, 90% interval 0.48 to 1.01. The upper end of that interval is the gene's LOEUF score, 1.01, which puts it in group 4 of 6, group 1 being the genes least tolerant of losing a copy. Missense variants: 299 observed, 332.78 expected, observed/expected ratio (o/e) 0.9, 90% interval 0.82 to 0.99. Synonymous variants: 113 observed, 119.98 expected, observed/expected ratio (o/e) 0.94, 90% interval 0.81 to 1.1.
Homologues: Orthologues: chimpanzee CD226 (99% identical), macaque CD226 (79% identical), rabbit CD226 (66% identical), pig CD226 (64% identical), dog CD226 (58% identical), mouse Cd226 (52% identical), rat Cd226 (51% identical), zebrafish cd226 (24% identical), tropical clawed frog cd226 (24% identical), Drosophila melanogaster Fas3 (14% identical). Paralogues in human: NECTIN4 (20% identical), NECTIN3 (20% identical), NECTIN1 (19% identical), NECTIN2 (18% identical), CADM2 (18% identical), CADM1 (17% identical), CADM3 (17% identical), CADM4 (16% identical), PVR (15% identical), TIGIT (14% identical), CD200 (12% identical), CRTAM (12% identical), and 2 more.
Diseases named in the same sentence as CD226 in open-access papers:
CD226 is named in the same sentence as 167 diseases in open-access papers, as found by Europe PMC text mining. Sharing a sentence is not in itself a finding about the gene and the disease. The quoted sentences say what the papers report.
melanoma (69 papers, 2013 to 2025). A malignant, usually aggressive tumor composed of atypical, neoplastic melanocytes. "In an adoptive transfer model of Pmel-1-CD8 + T cells into melanoma-bearing mice, mice given CD226-deficient Pmel-1-CD8 + T cells presented a decreased survival rate compared with that of mice given WT Pmel-1-CD8 + T cells." (PMID 39349829, 2024). "The high proportion of TIGIT+ Tregs and a high TIGIT/CD226 ratio in Tregs in the tumor immune microenvironment were associated with poor clinical prognosis in melanoma." (PMID 35474948, 2022). "According to a recent work, a decrease in its expression may be caused by tumoral activity and CD226+ on CD8+ T cells correlated with improved progression-free survival following in melanoma." (PMID 35743356, 2022). "Moreover, numbers of CD226+CD8+ TILs in pre-treatment tumor biopsies of melanoma patients are associated with improved progression-free survival following single anti-PD-1 therapy or anti-PD-1/anti-CTLA4 co-blockade." (PMID 34367161, 2021). "Single-cell RNA sequencing (RNAseq) of tumor-specific CD8+ T cells isolated from murine melanomas revealed that CD226+ Tumor Infiltrating Lymphocytes (TILs) exhibited an enrichment for genes associated with T cell activation and immune synapse formation compared to CD226- counterparts." (PMID 35874734, 2022). "It has been reported that sCD155 preferentially binds to CD226 and suppresses CD226-mediated NK cell cytotoxic activity, promoting melanoma metastasis." (PMID 35433470, 2022). "The proportion of highly suppressive CD25hiFoxp3+Treg cells is increased in melanoma patients who present a high TIGIT/CD226 ratio in tumor-infiltrating Treg cells." (PMID 33670993, 2021). "In our study, we initially demonstrated that CD226 was functional in NK targeting of our melanoma and ovarian tumour cell lines." (PMID 30908480, 2019). "We found that CD58 and CD155, which function as binding partners for the adhesion molecules CD2 and CD226, respectively, are broadly expressed in cell lines derived from human melanomas or B cell tumors." (PMID 29707134, 2018). "This association implies an involvement of CD226 in NK cell recognition of the allograft, analogously to the contribution of CD226 in recognition of melanoma cells." (PMID 26147651, 2015). "Our results may, in part, highlight the role of RUNX2 in EFF CD8+CD226+ immunosurveillance at the epithelial barriers, as previously reported in melanoma." (PMID 39777847, 2025). "Similar results were obtained with this combination approach in a B16 melanoma mouse model, where NK cell-specific TIGIT-deficiency resulted in the upregulation of DNAM-1 (CD226) expression by tumor-infiltrating NK cells and in tumor growth inhibition in CD155-deficient mice." (PMID 39339180, 2024). "Similarly, NK cell-specific TIGIT-deficiency resulted in a greater frequency of intra-tumoral NK cells expressing CD226 in the B16 melanoma mouse model." (PMID 34367161, 2021). "It has been reported that CD226 opposes TIGIT to disrupt Tregs in melanoma." (PMID 32983109, 2020). "It was demonstrated that CD226 + NK cells play an important role in the recognition of several types of human tumors, such as myeloma, melanoma, and ovarian carcinoma, and Recent studies have shown that CD226 may be one of the markers of mature NK cells." (PMID 32850777, 2020). "Given that the axis is active in immune surveillance of both melanoma and ovarian tumour cells, we established that platelet cloaked tumour cells, activated platelets and platelet releasate all function to suppress expression of CD226 and CD96 on the NK cell surface." (PMID 30908480, 2019). "Interestingly, CD8+ TILs downregulated CD226, the costimulatory counterpart to TIGIT, supporting an imbalance of TIGIT/CD226 expression in metastatic melanoma, which may contribute to melanoma-induced T cell dysfunction." (PMID 27461275, 2016).
melanoma (continued). "In melanoma, Tregs exhibit an elevated TIGIT/CD226 ratio, correlating with higher tumor-infiltrating Treg levels and worse clinical prognosis." (PMID 40723878, 2025). "In patients with melanoma treated with ICIs such as anti-PD-1 and/or anti-CTLA-4, better progression-free survival was observed in individuals with increased frequencies of CD226 + CD8+TILs." (PMID 39349829, 2024). "Particularly in melanoma, human Tregs display elevated TIGIT expression and decreased CD226 expression." (PMID 39349829, 2024). "In melanoma patients, increased TIGIT/CD226 ratio was observed in CD4+ Tregs compared with CD4+ effector T cells and was associated with highly suppressive TME and poor clinical outcomes." (PMID 35656508, 2022). "In a mouse melanoma model, CD8+TILs showed differential responsiveness to anti-PD-1 mAb treatment by CD226 expression." (PMID 33670993, 2021). "To investigate if the CD226/CD96-CD155/CD112 tumour cell recognition system is functional in the context of our ovarian and melanoma tumour cells we blocked each component with commercial mAb and performed NK cell functional assays." (PMID 30908480, 2019). "While it was not possible to detect PRAME-specific responses against the K562 HLA-A2+ cells or the 518A2 melanoma cells using the standard reporter, the CD2+CD226+ J76 PRAME TPR were stimulated by endogenously processed PRAME antigen expressed by these cells." (PMID 29707134, 2018). "Testing 75 SLNs and regional LNs from patients with melanoma revealed a negative correlation between the CD226:TIGIT ratio on CD8 T cells and the DCCD (P < 0.0001, Pearson’s correlation)." (PMID 40379833, 2025). "In a mouse melanoma model, anti-PD-1 therapy was unable to rescue effector functions of Tex cells lacking CD226, implying that the CD226- Tex group displayed a more terminally exhausted profile." (PMID 37398674, 2023). "Moreover, this increase in intratumour NK cells upon ITPP treatment corresponds to an increase in the numbers of activated (CD45+CD49b+CD226+) NK cells, as estimated by flow cytometry after ITPP treatment in melanoma‐bearing mice." (PMID 33624446, 2021). "Notably, IL-15 can increase the expression of both CD226 and TIGIT by intra-tumoral NK cells, and combination therapy of IL-15 and TIGIT blockade increased cytotoxicity of NK cells against melanoma and suppressed lung metastasis in mouse melanoma models." (PMID 34367161, 2021). "Deregulation of the TIGIT/CD226/CD155 axis was described in several tumors: TIGIT+ tumor infiltrating CD8+ T cells could be detected in small-cell lung cancers, colorectal cancers and melanoma, and TIGIT inhibition was recently shown to increase T cell functions of melanoma specific CD8+ T cells." (PMID 32155826, 2020). "NY-ESO-1-specific CD8+TILs express low levels of CD226 and high levels of TIGIT and PD-1 in melanoma patients, but this imbalance is not found in circulating CD8+T cells regardless of specificity for NY-ESO-1." (PMID 33670993, 2021). "However, the CD226 signaling pathway was involved in intercellular signal communication in the C2/C4 subpopulations in primary lesions, while no CD226-NECTIN signal interaction was detected in the melanoma subpopulations in microsatellite lesions." (PMID 40866912, 2025).
autoimmune disease (40 papers, 2011 to 2025). A disorder resulting from loss of function or tissue destruction of an organ or multiple organs, arising from humoral or cellular immune responses of the individual to their own tissue constituents. "Previous studies have indicated that a single nucleotide polymorphism (SNP) in CD226 (rs763361) is related to various autoimmune disorders, such as T1D, rheumatoid arthritis (RA), celiac disease, and psoriasis." (PMID 40957221, 2025). "Genome-wide association studies (GWAS) have revealed that CD226 is related to susceptibility to several autoimmune diseases, including T1D." (PMID 40957221, 2025). "Genetic polymorphisms and the dysregulated expression of CD226 are closely associated with susceptibility to autoimmune diseases, infectious diseases, allergic diseases, and cancer progression." (PMID 40723878, 2025). "Genome-wide association studies (GWAS) have confirmed that polymorphisms in the CD226 gene are associated with susceptibility to a range of autoimmune diseases, including T1D." (PMID 40957221, 2025). "CD226, a co-stimulatory receptor implicated in the pathogenesis of multiple autoimmune diseases including systemic lupus erythematosus (SLE), rheumatoid arthritis(RA), and pSS, regulates immune cell activation." (PMID 40787453, 2025). "Genetic polymorphisms within the CD226 gene have been associated with serval autoimmune diseases, including multiple sclerosis." (PMID 38521921, 2024). "CD226 polymorphisms are also associated with a number of autoimmune diseases, including type 1 diabetes, rheumatoid arthritis, systemic lupus erythematosus, and Sjogren’s syndrome." (PMID 35273617, 2022). "Our prior work identified the autoimmune disease risk-associated locus and costimulatory molecule, CD226, as being highly expressed not only on effector T cells but also, interferon-γ (IFN-γ) producing peripheral Tregs (pTreg)." (PMID 35693814, 2022). "The TIGIT/CD226 pathway has been linked genetically to several autoimmune diseases, including MS, RA, and T1D." (PMID 34298735, 2021). "Genome-wide association studies have linked allelic variants in the TIGIT/CD226 pathway to several autoimmune diseases such as type 1 diabetes, rheumatoid arthritis, and multiple sclerosis." (PMID 33413573, 2021). "A SNP in CD226 (rs763361) has been associated with genetic susceptibility to multiple autoimmune diseases including type 1 diabetes, multiple sclerosis, and rheumatoid arthritis." (PMID 33013915, 2020). "Genetic polymorphisms in CD226 have been associated with susceptibility to type 1 diabetes and other autoimmune diseases." (PMID 33013915, 2020). "As an adhesion molecule, CD226 mediates cellular adhesion during pathological inflammation, and accumulating reports have shown that CD226 is associated with several autoimmune diseases." (PMID 32983109, 2020). "These three single nucleotide polymorphisms of CD226 gene have been confirmed to be related to the susceptibility of a variety of autoimmune diseases." (PMID 32850777, 2020). "Until now, genetic approaches have revealed that CD226 Gly307Ser (rs763361) polymorphism was significantly associated with several different autoimmune diseases and the risk of multiple autoimmune diseases." (PMID 25685070, 2015). "It remains to assess the efficacy of inhibition of DNAM-1 in vivo in other autoimmune diseases, in which CD226 was identified as a susceptibility genetic factor, such as type 1 diabetes and systemic lupus erythematosus." (PMID 25685070, 2015). "In sequence, two CD226 variants that were previously related to autoimmune diseases were genotyped in 531 T1D patients and 590 controls." (PMID 24891767, 2014). "Reinforcing the role of CD226 in autoimmune disorders, a three-variant haplotype in CD226, rs763361-rs34794968-rs727088, was associated with systemic lupus erythematosus (SLE) and systemic sclerosis-related pulmonary fibrosis." (PMID 24891767, 2014).
autoimmune disease (continued). "Since CD226 expression levels on lymphocytes have been implicated in autoimmune diseases further research is necessary to understand its role in the myeloid compartment during such processes." (PMID 23029029, 2012). "CD226 genetic variants have been associated with a number of autoimmune diseases and recently with systemic sclerosis (SSc)." (PMID 22531499, 2012). "Nonsynonymous single nucleotide polymorphism rs763361/Gly307Ser in exon 7 of CD226 has been associated with multiple autoimmune diseases including T1D, MS and possibly AITD and RA." (PMID 21750737, 2011). "Additionally, genomic variants in IL7R and CD226 have been associated with other autoimmune diseases, such as type 1 diabetes and rheumatoid arthritis." (PMID 40076709, 2025). "The direction of effect of CD226 expression on autoimmune disease risk is of reduced expression increasing disease risk, suggesting less robust NK cell responses (potentially directed at viral pathogens or autoreactive T cells) increases the risk of autoimmunity." (PMID 35835762, 2022). "The study of CD226 gene polymorphism and autoimmune disease susceptibility has entered a new stage." (PMID 32850777, 2020). "The CD226 gene is a confirmed susceptibility gene for T1D and other autoimmune disorders." (PMID 30774629, 2019). "Thus, the CD226 rs763361/Gly307Ser non-synonymous polymorphism was first correlated to type 1 diabetes susceptibility, later to multiple autoimmune diseases and recently, to SSc." (PMID 22531499, 2012). "Our findings here elucidate the mechanisms by which CD226 contributes to type 1 diabetes and support future translational efforts to block CD226 signaling in individuals at-risk for type 1 diabetes and other autoimmune diseases with shared pathogenic mechanisms." (PMID 33013915, 2020). "The TIGIT/CD226 pathway has been associated with several human autoimmune diseases and studies in mice demonstrate that interference in this pathway may be an attractive approach to modulate autoimmune diseases." (PMID 24376654, 2013). "The expression levels of TIGIT and CD226 depend on the T cell subset and activation level, and an increasing number of studies have demonstrated the importance of the TIGIT/CD226 axis in tumors and autoimmune diseases." (PMID 39349422, 2024). "Among the susceptibility regions for autoimmune diseases, we evaluated the polymorphisms of four genes (IL7R, CAPSL, CD226, and CLEC16A) and found the SNPs within two of these genes, IL7R and CAPSL, to be significantly associated with AITDs." (PMID 38612837, 2024). "On the other hand, our results seem to discard the influence in AITDs susceptibility of rs3194051 for IL7R, rs763361 for CD226, and rs725613 for CLEC16A SNPs previously associated with other autoimmune diseases." (PMID 38612837, 2024). "The NK cell-specific eQTL for CD226 (peak eSNP: rs1788098, p = 1.92 × 10−19) colocalises with genetic loci for a range of haematological indices and autoimmune diseases; including IBD and T1DM." (PMID 35835762, 2022). "Further research is needed to determine if CD226- Tregs will provide increased purity and stability in patients with active autoimmune disease." (PMID 35693814, 2022). "similarly observed that Cd226 KO reduced disease severity in an experimental autoimmune encephalomyelitis (EAE) mouse model of MS, further highlighting the role of CD226 in autoimmune disease pathogenesis." (PMID 35693814, 2022). "We expand on these findings, leveraging our NK eQTL data to perform TWAS in five autoimmune diseases, defining novel roles for NK cell expression of CD226 and TMEM163 in systemic lupus erythematosus and primary biliary cirrhosis." (PMID 35835762, 2022). "The main difference between our study and previous studies investigating TIGIT or CD226 in autoimmune diseases is that we simultaneously explored the T cells expired molecular, TIGIT, as well as its competitive receptor, CD226." (PMID 32793241, 2020).